MIR501 (microRNA 501)
Synonyms: hsa-mir-501; MIRN501; mir-501
Gene: MicroRNA gene on chromosome X (50,009,722 to 50,009,805, forward strand). Ensembl gene ENSG00000211538.
Gene Ontology:
Biological process: miRNA-mediated post-transcriptional gene silencing
Cellular component: RISC complex
Homologues: Orthologues: chimpanzee ptr-mir-501 (100% identical), guinea pig MIR501 (86% identical), mouse Mir501 (85% identical). Paralogues in human: MIR500A (89% identical), MIR502 (83% identical), MIR500B (82% identical).
Diseases named in the same sentence as MIR501 in open-access papers:
MIR501 is named in the same sentence as 1 disease in open-access papers, as found by Europe PMC text mining. Sharing a sentence is not in itself a finding about the gene and the disease. The quoted sentences say what the papers report.
schizophrenia (1 paper, 2022). A major psychotic disorder characterized by abnormalities in the perception or expression of reality. "To investigate the function of schizophrenia-related down-regulated miR-501-3p, we generated Mir501–knockout (KO) mice by inverting the Mir501 gene and flanking it with the FLEx cassette, resulting in deficiencies in miR-501-3p and miR-501-5p expression in the absence of Cre." (PMID 35984881, 2022).